NEU1 (neuraminidase 1)
Diseases named in the same sentence as NEU1 in open-access papers (continued):
Sharing a sentence is not in itself a finding about the gene and the disease.
colon adenocarcinoma (1 paper, 2022). "Moreover, the NEU-1 overexpression in colon adenocarcinoma HT-29 cells decreased the cell migration and the invasion of the human CRC cells." (PMID 36230790, 2022).
coronary artery disease (1 paper, 2021). "Researchers discovered that NEU1 was highly expressed in the heart of patients with coronary artery disease, and NEU1 knockdown notably protected cardiomyocytes from ischemic injury." (PMID 34977042, 2021).
dementia (1 paper, 2022). Loss of intellectual abilities interfering with an individual's social and occupational functions. "In one study, Neu1−/− mice showed a brain phenotype with signs of early aging, with the presence of amyloid deposits similar to the plaque that is characteristic of AD, which is the most common cause of dementia among older adults." (PMID 35847014, 2022).
depression (1 paper, 2026). "By prioritizing UCP2, SOD1, HK2, NDUFS4, and NEU1, our findings highlight novel, immune-mediated pathways in depression and nominate promising targets for future diagnosis and therapeutic intervention." (PMID 41601681, 2026).
eczema (1 paper, 2015). "Furthermore, the study identified for the first time that the PROZ and NEU1 genes are potential predictors of eczema." (PMID 26199674, 2015). "Novel genes associated with eczema risk were identified (e.g., the PROZ and NEU1 genes)." (PMID 26199674, 2015).
energy metabolism disorder (1 paper, 2022). "Cardiomyocyte-specific NEU1 deficiency can alleviate MI-induced myocardial remodeling, oxidative stress, and mitochondrial energy metabolism disorder." (PMID 35548408, 2022).
glomerulonephritis (1 paper, 2024). A renal disorder characterized by damage in the glomeruli. "As NEU1 regulates the maintenance and repair of glomerular filtration membranes, NEU1 deficiency can lead to the damage of these membranes, subsequently paving the way for the development of urological disorders, such as glomerulonephritis, nephrotic syndrome, etc.." (PMID 39194692, 2024).
glucose metabolic disorders (1 paper, 2025). "Given the essential role of NEU1 in DOX‐induced glucose metabolic disorders, we clarify the molecular mechanism of Neu1 upregulation under DOX treatment." (PMID 40411250, 2025). "Collectively, these findings suggest a promotive role of Neu1 in chemotherapy‐evoked glucose metabolic disorders and cardiotoxicity." (PMID 40411250, 2025).
glucosuria (1 paper, 2023). "While Neu1-null mice did indeed have higher serum glucose than WT animals, the levels observed are not high enough to cause glucosuria." (PMID 37698928, 2023).
GM2 gangliosidosis (1 paper, 2023). A group of recessively inherited diseases characterized by the intralysosomal accumulation of G(M2) GANGLIOSIDE in the neuronal cells. "Additionally, it is possible that in the absence of NEU3, both NEU4 and NEU1 may partially compensate for this sialidase loss, as all neuraminidase activity has been shown to be increased in mouse models of GM2 gangliosidosis." (PMID 38098938, 2023).
hepatitis B (1 paper, 2021). "Previous studies from two different groups have implied that NEU1 is upregulated in hepatitis B-associated HCC, which supported our findings." (PMID 34513919, 2021).
Immunodeficiency (1 paper, 2019). Failure of the immune system to protect the body adequately from infection, due to the absence or insufficiency of some component process or substance. "Neu1 deficiency in humans leads to the reduced ability of immune cells to produce cytokines leading to partial immunodeficiency." (PMID 31649671, 2019).
interstitial lung disease (1 paper, 2024). A diverse group of lung diseases that affect the lung parenchyma. "Consistent with this, Neu1 expression was increased in lung tissue samples from patients with interstitial lung disease (ILD), correlated with increased inflammation and mucus production in the airways." (PMID 38500102, 2024).
metabolic syndrome (1 paper, 2022). A cluster of metabolic risk factors for CARDIOVASCULAR DISEASES and TYPE 2 DIABETES MELLITUS. "Consequently, NEU-1 could represent a common pharmacological target to treat putative metabolic syndrome-associated cancers like colorectal, hepatocellular and postmenopausal breast cancer." (PMID 36230790, 2022).
metachromatic leukodystrophy (1 paper, 2025). A rare lysosomal storage disorder characterized by intralysosomal accumulation of sulfatides in various tissues, leading to progressive deterioration of motor and neurocognitive function. "The secondary NEU1 deficiency occurred in the brains of all analyzed mouse models of neurological MPS (MPS I, II, IIIA, IIIB, IIIC) but not in the models of other LSDs (metachromatic leukodystrophy, ML IV, Tay-Sachs, or NPC1)." (PMID 40540388, 2025).
metastatic disease (1 paper, 2016). "The potential clinical implications of these studies suggest that selectively targeting Neu4 and Neu1 could modify the glycosylation state of cell surface proteins, thus reducing tumor growth and preventing metastatic disease." (PMID 27608845, 2016).
Miscarriage (1 paper, 2021). A pregnancy that ends at a stage in which the fetus is incapable of surviving on its own, defined as the spontaneous loss of a fetus before the 22th week of pregnancy. "The expression of four mentioned carbohydrate Lewis antigens and their potential modulators, ST3GAL6 and NEU1, in the placenta of patients with miscarriages was significantly different from the normal pregnancy." (PMID 34135905, 2021). "Immunohistochemical staining further indicated that Lewis antigens were downregulated in miscarriage groups and key modulators including, ST3GAL6 and NEU1, might be responsible for these alterations." (PMID 34135905, 2021).
non-small cell lung carcinoma (1 paper, 2020). A group of at least three distinct histological types of lung cancer, including non-small cell squamous cell carcinoma, adenocarcinoma, and large cell carcinoma.
parasite (1 paper, 2019). "Such events strongly confirm the importance of Neu1 in modulation of TLR4 sialylation during parasite infection resulting in impairment of innate immune response." (PMID 31649671, 2019). "This led us to further investigate the effect of Neu1 silencing on TLR4 during this parasite infection." (PMID 31649671, 2019). "Here, we have established a specific novel role of a mammalian lysosomal sialidase (Neu1) on the regulation of TLR4 sialylation and its impaired functioning during this parasite infection." (PMID 31649671, 2019).
pericarditis (1 paper, 2026). An inflammatory process affecting the pericardium. "Among them, elevated levels of NEU1, GDNF, and LAT increased the risk of pericarditis, whereas higher levels of CASP8, ZFYVE27, and NAPA decreased the risk of pericarditis." (PMID 41674924, 2026).
periodontitis (1 paper, 2023). An acute or chronic inflammatory process that affects the tissues that surround and support the teeth. "The ratio of Neu1 was significantly increased in patients with periodontitis." (PMID 37639212, 2023).
psoriasis (1 paper, 2024). An autoimmune condition characterized by red, well-delineated plaques with silvery scales that are usually on the extensor surfaces and scalp. "Among these proteins, AIF1, FCGR3A (Fc gamma receptor IIIa), and NEU1 (neuraminidase 1) were considered the strongest candidates for psoriasis risk (PP.H4 = 1)." (PMID 39883516, 2024). "Based on the GWAS data, further MR analysis and colocalization analysis genetically predicted that AIF1, FCGR3A, NEU1, HSPA1A, TNXB (Tenascin XB), and ABO were associated with psoriasis risk." (PMID 39883516, 2024). "According to this study, NEU1, TNXB, and ABO were also related to psoriasis risk." (PMID 39883516, 2024). "MR analyses unveiled 19 unique circulating proteins that were associated with psoriasis, among which only AIF1, FCGR3A, NEU1, HSPA1A, TNXB, and ABO were the potential proteins that interacted with psoriasis risk after being analyzed with high evidence of colocalization (PP.H4 > 0.9)." (PMID 39883516, 2024).
rhabdomyosarcoma (1 paper, 2021). A rare aggressive malignant mesenchymal neoplasm arising from skeletal muscle. "Evidence of the effects of deregulated lysosomal exocytosis on malignant transformation have been shown in human rhabdomyosarcoma cells with low NEU1 expression." (PMID 33718382, 2021). "Indeed, this was demonstrated in aggressive rhabdomyosarcoma cells with low expression of NEU1, where increased lysosomal exocytosis led to excessive release of exosomes carrying pro-tumorigenic signals." (PMID 33718382, 2021).
sarcoma (1 paper, 2022). A usually aggressive malignant neoplasm of the soft tissue or bone. "Notably, human MYH11 protein, which is normally not expressed in RMS, is a marker of sarcoma pleomorphism, and an effector of lysosomal exocytosis downstream of Neu1 downregulation." (PMID 36127469, 2022).
Shock (1 paper, 2022). The state in which profound and widespread reduction of effective tissue perfusion leads first to reversible, and then if prolonged, to irreversible cellular injury. "Neu1 was associated with septic shock and significantly correlated with the sequential organ failure assessment (SOFA) score." (PMID 36304125, 2022).
steatosis (1 paper, 2022). Increased lipid within the cytoplasm of cells. "However, the role of NEU-1 in steatosis remains controversial." (PMID 36230790, 2022).
uveitis (1 paper, 2022). An inflammatory process affecting a part of or the entire uvea. "Furthermore, horses with recurrent uveitis had higher levels of NEU1 in Müller glial cells in the retina." (PMID 36291734, 2022). "Therefore, NEU1 might be a new marker of activated Müller glial cells in uveitis." (PMID 36291734, 2022).
visceral leishmaniasis (1 paper, 2019). A severe form of leishmaniasis characterized by irregular bouts of fever, substantial weight loss, swelling of the spleen and liver, and anemia (which may be serious). "Thus, Neu1 on the cell surface may be one of the crucial factors in the suppression of the immune response during active visceral leishmaniasis in humans." (PMID 31649671, 2019).
cancer (53 papers, 2009 to 2025). A tumor composed of atypical neoplastic, often pleomorphic cells that invade other tissues. "Based on previous work, a critical role of neuraminidase-1 (Neu-1) in the regulation of a number of tyrosine kinase receptors has been implicated in cancer cell proliferation and metastasis." (PMID 40227834, 2025). "The inhibition of Neu-1 by oseltamivir phosphate (OP) was demonstrated to decrease the downstream signaling of the receptor–ligand binding implicated in cancer progression." (PMID 40227834, 2025). "Taken together, the findings in the report identified, for the first time, that neuraminidase-1 (Neu1) is an important cancer-targeting enzyme that is unaffected by the activating mutations in cancer cells." (PMID 39451257, 2024). "Dysregulation of Neu1 activity has been implicated in several diseases, including cancer, metabolism disorder, neurodegenerative disorders, and respiratory diseases." (PMID 38500102, 2024). "There are four sialidase enzymes (NEU1-4), and individual sialidases have also been associated with certain cancer types." (PMID 36077781, 2022). "NEU1 is a tumor progression inhibitor and was recently described as a gene closely associated with metastatic potential and invasiveness in some cancer types." (PMID 35354905, 2022). "Knowing that dimerization is required for its activity, interfering peptides targeting specifically TM2 domain of Neu-1 constitute novel key tools to selectively block Neu-1 activity and its linked biological effects in cancer." (PMID 32351895, 2020). "For example, NEU1 has been linked to cancer metastasis, as it is involved in facilitating the epithelial to mesenchymal transition in cancer cells." (PMID 29912148, 2018). "Here, OP is used in the formulation because of its anticancer drug properties targeting mammalian neuraminidase 1 (Neu1) involved in multistage tumorigenesis for pancreatic, triple negative breast and ovarian cancers." (PMID 29560107, 2018). "Among them, NEU1 is implicated in multiple diseases, including lysosomal storage disorders, infections, cancers, and neurodegenerative disorders, due to its regulation of critical signaling pathways, making it a potential therapeutic target for cancer and immune-related diseases." (PMID 41154604, 2025). "Altered NEU1 expression has been linked to the degree of tumor progression in various cancers." (PMID 39194692, 2024). "This may be related to the regulation of cancer-associated pathways and the inhibition of immune function by NEU1." (PMID 34513919, 2021). "Perhaps, overexpression of Neu1 in metabolically active cancer cells may produce a variant with different phenotypes." (PMID 27029067, 2016). "In this scenario, tumor cells, cancer-associated fibroblasts, and cancer-associated adipocytes may together sustain cancer progression and chemo-resistance by fueling metabolism and maintaining a pro-fibrotic microenvironment downstream of low NEU1 activity." (PMID 36127469, 2022). "Activated Neu1 hydrolytically cleaves α-2,3-linked sialic acid(s) from the receptor's ectodomain, the desialylation process allowing for the removal of steric hindrance and thus for proper receptor dimerization and activation of its signaling cascade networks within the cancer cell." (PMID 26932374, 2014). "For instance, C1QTNF3 regulates inflammatory pathways, NEU1 modulates cellular signaling and shows therapeutic potential for cancer and immune disorders, and GPx3 is known for its antioxidant and anti-inflammatory properties." (PMID 40243471, 2025). "In the cellular lipid metabolism process, Bacteroides_sartorii was positively correlated with lipid metabolism-related gene of Mttp, cancer-related genes of Rbp2, and Dhrs9, but was also negatively correlated with cancer-related genes of Neu1 and Hmgcs2." (PMID 39727670, 2025).
cancer (continued). "This CB1 heterodimerization with NMBRs activates Neu-1, which can alter the glycosylation state of receptors, thereby modulating downstream signaling pathways that contribute to cancer progression." (PMID 39851499, 2025). "There are also studies showing that the high expression of NEU1 plays a positive role in cancer inhibition, as illustrated by the inhibited progression of colon and cervical cancers." (PMID 39194692, 2024). "NEU-1 exhibited pronounced effects on the development of several cancers by regulated the cancer cells' proliferation and migration, including hepatocellular cancer, pancreatic carcinoma and breast cancer." (PMID 38500102, 2024). "Increased cancer prevalence has also been reported in carriers of a potentially pathogenic variant of an LSD gene, namely CLN3, SGSH, GUSB, NEU1, and, to a lesser extent, in other genes." (PMID 39404425, 2024). "Multiple receptors involved in signaling pathways implicated in cancer progression, such as EGFR, TrkA, and TOLL-like receptors, are associated with NEU1." (PMID 39194692, 2024). "The expression of NEU1 tended to decrease in cancer cells, and it was particularly low in KK47 cells." (PMID 38255300, 2024). "NEU1 is highly expressed in various cancers, such as liver cancer, pancreatic cancer, ovarian cancer, and melanoma." (PMID 37372117, 2023). "Following Neu-1 inhibition, OP exerted its anti-cancer effects through increased E-cadherin expression and decreased VE-cadherin and N-cadherin in human pancreatic cells (PANC1) as EMT and E-cadherin loss." (PMID 36831374, 2023). "In cancers that overexpress NEU1 the enzyme has been found to act as a negative regulator of migration through disruption of β1-and β4-integrin interactions." (PMID 35281276, 2022). "We have previously reported that repurposing ASA as an anti-cancer agent can upend critical targets involved in multistage tumorigenesis regulated by mammalian Neu-1." (PMID 35326525, 2022). "Exploiting the low NEU1 > high lysosomal exocytosis axis, we developed a single-cell approach that relied on the increased levels of the Neu1 substrate Lamp1 at the PM of cancer and stromal cells." (PMID 36127469, 2022). "As with all neuraminidases, Neu-1 hydrolyzes links on growth factor receptors for cancer cells, making Neu-1 a vital regulator of glycosylated receptors." (PMID 35326525, 2022). "Altogether, these data indicate that NEU-1 plays a key role not only in metabolic disorders, but also in the development of several cancers which make NEU-1 a pharmacological target of high potential in these physiopathological contexts." (PMID 36230790, 2022). "Altogether, these studies indicate that NEU-1 plays a key role not only in the development of several cancers but also in metabolic disorders, which make NEU-1 a pharmacological target of high potential in these physiopathological contexts." (PMID 36230790, 2022). "In this review, we will focus on the role of NEU1 in several cancers and in metabolic diseases, which leads this protein to be a very interesting target in these physiopathological contexts." (PMID 36230790, 2022). "This sialidase is not only required for the biological effects that are mediated by the elastin-derived peptides on several metabolic disorders, but NEU-1 is also involved in the development of various cancers." (PMID 36230790, 2022). "We showed that ASA exerts anti-cancer effects by targeting and inhibiting mammalian neuraminidase-1 (Neu-1)." (PMID 35326525, 2022). "Previous research reported that sialidase NEU1 is expressed at different levels in normal tissues and is strongly deregulated in different cancer, which showed the potential application of NEU1 in tumor diagnosis and therapy." (PMID 34513919, 2021). "Published data on expression and function of NEU1 in various types of cancer appear somewhat contradictory." (PMID 32164705, 2020).